EFNB1 (ephrin B1)
Description:
Cell surface transmembrane ligand for Eph receptors, a family of receptor tyrosine kinases which are crucial for migration, repulsion and adhesion during neuronal, vascular and epithelial development. Binding to Eph receptors residing on adjacent cells leads to contact-dependent bidirectional signaling into neighboring cells. Shows high affinity for the receptor tyrosine kinase EPHB1/ELK. Can also bind EPHB2 and EPHB3. Binds to, and induces collapse of, commissural axons/growth cones in vitro (By similarity). May play a role in constraining the orientation of longitudinally projecting axons (By similarity).
Synonyms: ELK-L; EFL3; EPLG2; LERK2; CFND; CFNS; EFB1
Tractability: Antibody: UniProt places it where antibodies can reach, with high confidence; its Gene Ontology location is reachable by antibodies, with high confidence; UniProt predicts a signal peptide or a membrane-spanning region; the Human Protein Atlas places it where antibodies can reach. PROTAC: ubiquitination databases record sites on it; its protein half-life has been measured.
Gene: Protein-coding gene on chromosome X (68,828,992 to 68,842,160, forward strand). Ensembl gene ENSG00000090776.
Subcellular location: Cell membrane; Membrane raft; Cell membrane (Ephrin-B1 C-terminal fragment); Nucleus (Ephrin-B1 intracellular domain)
Subcellular location (Human Protein Atlas): Plasma membrane
Pathways (Reactome):
Developmental Biology: EPH-Ephrin signaling; EPH-ephrin mediated repulsion of cells; EPHB-mediated forward signaling; Ephrin signaling
Gene Ontology:
Molecular function: ephrin receptor binding; protein binding
Biological process: axon guidance; cell adhesion; cell-cell signaling; ephrin receptor signaling pathway
Cellular component: cell surface; extracellular exosome; membrane raft; nucleus; plasma membrane; glutamatergic synapse; presynaptic membrane; synapse; cytoplasm; membrane
Gene-disease validity (ClinGen):
ClinGen rates the evidence that EFNB1 causes each of these diseases.
craniofrontonasal syndrome (X-linked): Definitive.
Homologues: Orthologues: chimpanzee EFNB1 (99% identical), macaque EFNB1 (98% identical), pig EFNB1 (97% identical), guinea pig EFNB1 (97% identical), mouse Efnb1 (96% identical), rat Efnb1 (95% identical), rabbit EFNB1 (94% identical), tropical clawed frog efnb1 (70% identical), zebrafish efnb1 (67% identical), Drosophila melanogaster Ephrin (27% identical), Caenorhabditis elegans vab-2 (21% identical), Caenorhabditis elegans efn-4 (17% identical), and 2 more. Paralogues in human: EFNB2 (53% identical), EFNB3 (39% identical), EFNA2 (16% identical), EFNA1 (16% identical), EFNA5 (16% identical), EFNA3 (15% identical), EFNA4 (13% identical).
Diseases named in the same sentence as EFNB1 in open-access papers:
EFNB1 is named in the same sentence as 104 diseases in open-access papers, as found by Europe PMC text mining. Sharing a sentence is not in itself a finding about the gene and the disease. The quoted sentences say what the papers report.
craniofrontonasal syndrome (40 papers, 2006 to 2025). "Perhaps the most convincing evidence of association of Müllerian duct anomalies with Eph-ephrin signaling is demonstrated in Craniofrontonasal syndrome caused by pathogenic variations in EFNB1 encoding ephrin B1." (PMID 41099950, 2025). "Craniofrontonasal syndrome is the last category of craniosynostosis, and it is characteristic of mutations in EFNB1." (PMID 38673496, 2024). "An X‐linked female limited inheritance pattern is quite exceptional and only known from craniofrontonasal syndrome caused by EFNB1 mutations (MIM# 304110) and epilepsy in females caused by PCDH19 mutations variants (MIM# 300088)." (PMID 35001458, 2022). "Mutations in EFNB1 cause craniofrontonasal syndrome, whereas mice heterozygous for Efnb1 display skull defects that are thought to be mediated by inhibition of normal gap junctional communication via Cx43 at ectopic ephrin-Eph boundaries." (PMID 34403370, 2021). "A variant in the EFNB1 gene was detected in a male with classic features of craniofrontonasal syndrome by HTS analysis." (PMID 33288889, 2021). "Mutations in EFNB1 cause craniofrontonasal syndrome, which features cleft lip and palate among other clinical manifestations." (PMID 28877219, 2017). "EFNB1 has previously been associated with craniofrontonasal syndrome (MIM #304110), a severe craniofacial midline defect that is only expressed in female carriers." (PMID 27138190, 2016). "In humans, mutations inEFNB1, the gene coding for ephrin-B1, leads to craniofrontonasal syndrome (CFNS)." (PMID 27092247, 2016). "EFNB1 is known to play a role in facial development: mutations on EFNB1 are responsible for the majority of cases of craniofrontonasal syndrome (CFNS), whose features can include cleft lip and palate." (PMID 25713581, 2015). "Total disruption of the ephrin B1 gene in mice results in perinatal lethality and defects in skeletal patterning while mutations of the ephrin B1 gene in humans cause craniofrontonasal syndrome." (PMID 23874863, 2013). "Craniofrontonasal syndrome (CNFS) is an X-linked disorder caused by mutations in the EFNB1 gene in which, paradoxically, heterozygous females are more severely affected than hemizygous males." (PMID 23509643, 2013). "Intriguingly, genetic analysis revealed that several mutations in human ephrin-B1 gene are linked to familial and sporadic forms of craniofrontonasal syndrome (CFNS)." (PMID 16930449, 2006). "In addition, this theory also explains the same pattern of inheritance of another X-linked genetic disease, the craniofrontonasal syndrome (CFNS) caused by loss-of-function variants in the EFNB1 gene." (PMID 39457436, 2024). "However, we postulate that a very characteristic disease, i.e., craniofrontonasal dysplasia (CFND) resulting from pathogenic variants of the EFNB1, should be considered a standalone genetic disorder in which features other than CS guide the proper diagnosis." (PMID 35591945, 2022). "Interestingly, ephrinB1 is encoded by EfnB1, an X-linked gene associated with the human CranioFrontoNasal Syndrome (CFNS)." (PMID 24520368, 2014). "Interestingly, these studies uncovered a previously unknown link between FASDs and the EFNB1 gene that encodes ephrin B1, which plays a crucial role in neurodevelopment and the development of craniofrontonasal syndrome." (PMID 40862205, 2025). "Mutations in Ephrin-B1 lead to human craniofrontonasal syndrome (CFNS), an effect mediated by changing Cx43 distribution and inhibition of GJIC at ectopic Ephrin boundaries." (PMID 38534339, 2024). "Craniofrontonasal syndrome (CFNS), also known as craniofrontonasal dysplasia, is an X-linked inherited developmental malformation caused by mutations in the ephrin B1 (EFNB1) gene." (PMID 36558986, 2022). "Craniofrontonasal syndrome (CFNS) is a rare X-linked disorder that results from pathogenic variants in the EFNB1 gene." (PMID 34174922, 2021). "For example, mutations in EFNB1 were identified in craniofrontonasal syndrome (CFNS)." (PMID 36942388, 2023).
craniofrontonasal syndrome (continued). "Two additional examples are reported in the same review, which are related to a defect in the ephrin-B1 gene and to the craniofrontonasal syndrome, for which even heterozygous females are more severely affected than hemizygous mutant males." (PMID 33009476, 2020). "Mutations in EfnB1 are associated with a human syndrome called CranioFrontoNasal Syndrome (CFNS)." (PMID 24520368, 2014). "Mutations of EFNB1 cause the X-linked malformation syndrome craniofrontonasal syndrome (CFNS)." (PMID 20565770, 2010). "Mutations in EFNB1 (OMIM 300035), encoding the transmembrane protein ephrin-B1, have been detected in the majority of patients with familial and sporadic craniofrontonasal syndrome." (PMID 20565770, 2010). "Craniofrontonasal dysplasia due to EFNB1, an X-linked condition that does not manifest (fully) if hemizygous, is an example of an edge case that required the introduction of a specific cross-cutting inheritance qualifier (requires heterozygosity HP:0034343)." (PMID 37982373, 2024). "Similarly, ephrin B1 (EFNB1), a gene implicated in a craniosynostosis disorder known as craniofrontonasal syndrome, is predicted to be important in boundary maintenance." (PMID 35451466, 2022). "Several genes were reported only in syndromic cases; CHD7 (CHARGE syndrome), CR1 (van der Woude syndrome), EFNB1 (craniofrontonasal syndrome), KISS1R (Kallmann syndrome), MID1 (Opitz G/BBB syndrome), REN (van der Woude syndrome), and SOX9 (Pierre-Robin syndrome)." (PMID 31122291, 2019). "Craniofrontonasal syndrome (CFNS; MIM #304110) is a rare craniofacial disorder characterized by hypertelorism, a broad nasal root with a bifid nasal tip, orofacial clefting, and genital malformations caused by pathogenic variants in the X-linked gene EFNB1 (MIM *300035)." (PMID 40490530, 2025). "For example, craniofrontonasal syndrome (CFNS) is caused by a mutation in the gene EFNB1, which encodes for Ephrin B1, a protein whose signaling plays a role in pattern formation and cell migration during the developmental period." (PMID 35822151, 2022). "Craniofrontonasal syndrome (CFNS, OMIM #304110) is a form of frontonasal dysplasia that is caused by loss of function mutations in the EFNB1 gene, which is located on the X chromosome." (PMID 32092051, 2020). "Furthermore, a contiguous deletion of a region containing EFNB1, ‘Oligophrenin 1’ (OPHN1), PJA1 and EDA was reported in patients with craniofrontonasal syndrome." (PMID 28877219, 2017).
craniosynostosis (11 papers, 2017 to 2025). Craniosynostosis is defined as the premature fusion of one or more cranial sutures leading to secondary distortion of skull shape resulting in skull deformities with a variable presentation. "Mutations in EFNB1 disrupt normal cranial bone development, leading to craniosynostosis and other craniofacial abnormalities." (PMID 38396475, 2024). "Mutations in EFNB1 are associated with craniofrontonasal syndrome, another type of syndromic craniosynostosis." (PMID 38396475, 2024). "Frontonasal dysplasia and coronal craniosynostosis in humans are cranial defects caused by loss-of-function mutations in the EFNB1 gene coding for ephrin-B1." (PMID 36077474, 2022). "The genetic causes of syndromic craniosynostosis also include alterations in the TWIST1, ERF, and EFNB1 genes, which play a specific role in the development of this condition." (PMID 38396475, 2024). "Genes most commonly mutated in familial craniosynostosis include, besides FGFR2 and FGFR3, the twist family bHLH transcription factor 1 (TWIST1) and ephrin-B1 (EFNB1)." (PMID 37441579, 2023). "Loss of function mutations in EFNB1 lead to craniofronto-nasal syndrome (CFNS) a genetic condition characterized by a wide range of phenotypic effects including frontonasal dysplasia, craniofacial asymmetry, craniosynostosis, bifid nasal tip, grooved nails, wiry hair, and skeletal abnormalities." (PMID 35305552, 2022). "On the other hand, it would be important to include other genes, such as TCF12 (OMIM 600,480), MSX2 (OMIM 123,101), RAB23 (OMIM 606,144), and EFNB1 (OMIM 300,035), to determine their participation in craniosynostosis in the Mexican population." (PMID 32510873, 2020).
breast carcinoma (10 papers, 2016 to 2025). "Of note, Márquez-Ortiz described an ephrin-dependent (EFNB1/EPHB1) mechanism underlying an IL13RA2 function in breast cancer brain metastasis." (PMID 40663259, 2025). "Down-regulated genes in HER2-negative cell lines are directly linked to HER2 overexpression and HER2-positive breast cancers (e.g., Stat, Ptpn1, Pak1, Efnb1)." (PMID 34775465, 2021). "Some reports suggest the use of EFNB1 as a potential biomarker for tumor progression and therapy response in the brain and breast cancer." (PMID 35565468, 2022). "Ephrin-B1 was also shown to be important for EphB2-induced invasion in at least one breast cancer cell line." (PMID 34360867, 2021). "Higher expression of ephrin-B1 appears to be related to breast cancer metastasis and confers a poor prognosis." (PMID 34360867, 2021). "The expression of EFNB1 was related to the metastasis of breast cancer, and its enhanced expression conferred a poor prognosis." (PMID 30446011, 2018). "The elevated co-expression of NGFR, EFNB1, and APP was associated with longer overall and metastasis-free survival of patients with breast cancer." (PMID 30446011, 2018). "In breast cancer, in agreement with our data, it was recently reported that high expression of EFNB1 was positively correlated with lymph node metastasis and with the presence of HER2 receptor." (PMID 26673618, 2016). "Applying the Gene Set Analysis (GSA) we found that elevated expression of HRH1, EFNB1, KLK1, NRP2, and APP was associated with the basal-like subtypes of breast cancer as predicted by the MicMa cohort." (PMID 26673618, 2016). "The same finding was observed in the MCF10A-derived model of breast cancer progression, whereby both the invasive (CA1ACL1 and CA1DCL1) and the DCIS.com cell variants co-expressed higher levels of EphB2, EFNB1, and EFNB2 than the benign parental MCF10A cell line." (PMID 34360867, 2021). "Although we found that EPHB2 was the most promising candidate in our breast cancer cohorts, EPHB2 together with EPHB6, EPHA2, EPHA4 and the ligands EFNB1 and EFNB2 were important to define prognostic relevant clusters." (PMID 26870995, 2016). "We also suggest that EFNB1 and EFNB2 could be additional interesting candidates and revealed the clinical value of EPHB2 as a potential prognostic marker in breast cancer." (PMID 26870995, 2016). "Especially EPHA2, EPHA4, EFNB1, EFNB2, EPHB2, and EPHB6 and their co-expression in breast cancer." (PMID 26870995, 2016).
glioma (5 papers, 2017 to 2025). A benign or malignant brain and spinal cord tumor that arises from glial cells (astrocytes, oligodendrocytes, ependymal cells). "Ephrin-B1 is consistently upregulated in gliomas, where it promotes tumor progression by enhancing proliferation, migration, and invasion." (PMID 41200151, 2025). "Analogous findings have been reported for ephrins, with increased expression of ephrin-A3 and ephrin-A4 in ependymoma cell lines, of ephrin-B1 in medulloblastoma cell lines and rhabdomyosarcoma tumor cells, and of ephrin-B2 in gliomas and rhabdomyosarcoma tumor cells." (PMID 38612645, 2024). "Similarly, EphB2, by interacting with either ephrin-B1 or ephrin-B3, stimulates invasion in glioma cells." (PMID 34360867, 2021). "Functionally, ephrin-B1 silencing reduces GBM cell proliferation and migration, further supporting its oncogenic and immunomodulatory roles in high-grade gliomas." (PMID 41200151, 2025).
medulloblastoma (5 papers, 2018 to 2025). A malignant, invasive embryonal neoplasm arising from the cerebellum. "EphA6 exhibits subtype-specific expression in medulloblastoma, particularly enriched in subtype D, where it correlates with genes linked to axonal guidance and neuronal differentiation, such as Ephrin-B1, RND1, RND2, and SEMA3A." (PMID 41200151, 2025). "Ephrin-B2 has been reported to be expressed in all medulloblastoma tumors, while ephrin-B1, associated with more aggressive phenotypes, was expressed in 20% of the tumors." (PMID 38612645, 2024). "Elevated expression of EphA2, EphB2, and EphB4 in medulloblastoma cell line is linked to ephrin-B1 mediated invasion." (PMID 29682554, 2018). "For example, the medulloblastoma cell lines with high expression of EphB2 were stimulated by ephrin-B1, the cell adhesion ability in vitro was significantly decreased, and the invasion ability was increased." (PMID 35223830, 2022). "EphB2 and its ligand ephrin-B1 have been shown to be highly expressed in medulloblastoma tissue samples, and EphA2, EphB2, and EphB4 are overexpressed in medulloblastoma cell lines." (PMID 33050158, 2020). "Moreover, subsequent studies have confirmed the crucial role of EPH/ephrin signaling in the medulloblastoma metastatic capacity; EPHB2 and ephrin-B1—except for being overexpressed—were also found to associate with invasive and metastatic tumor subtypes." (PMID 38612645, 2024). "While ephrin-B1 is uniquely dysregulated in medulloblastoma, differential effects of ephrin-B1 and ephrin-B2 knockdown on phosphorylation of EphB1/B2 and Src suggest alterations in reverse signaling in medulloblastoma cells." (PMID 29682554, 2018). "Regarding EPH/ephrin members’ expression, upregulation of EPHB2 and ephrin-B1 has been reported in tumor samples compared to normal cerebellum, while EPHA2, EPHB2, and EPHB4 showed overexpression in medulloblastoma cell lines." (PMID 38612645, 2024). "Stimulation with ephrin-A1 failed to elicit notable phenotypic effects, whereas ephrin-B1 induced modest activation of type A Eph receptors in Uw-402, suggesting cross-reactivity and ligand promiscuity within the Eph/ephrin system in medulloblastoma." (PMID 41200151, 2025).
Obesity (5 papers, 2013 to 2024). Accumulation of substantial excess body fat. "(2022) investigated the role of EphB2/ephrin-B1 signaling in the development and progression of obesity-associated CRC." (PMID 38651144, 2024). "In obesity, reductions in adipose EFNB1 levels accelerate the vicious cycle of adipose tissue inflammation." (PMID 39532838, 2024). "In obesity, the ephrin-B1 expression in normal colon mucosa is downregulated, leading to decreased cell apoptosis and carcinogenesis." (PMID 35949596, 2022). "The findings suggested that obesity results in disruption of EphB2/ephrin-B1 signalling, promoting colorectal cancer development and progression." (PMID 35949596, 2022). "TNF-α, which is increased in obesity, significantly reduced EfnB1 mRNA expression level, suggesting that this cytokine is one of factors accounting for the low expression of EFNB1 in obese adipose tissue." (PMID 24098442, 2013). "In obesity, reduction in ephrin-B1 levels may lead to apoptosis inhibition in the crypt-villus axis and subsequent development and progression of adenoma." (PMID 35949596, 2022). "It was found that ephrin-B1 expression at the top of the crypt was downregulated in obesity and that the dysregulated EphB2/ephrin-B1 signalling may disrupt cell apoptosis and carcinogenesis." (PMID 35949596, 2022). "It has been shown that obesity-related inflammatory cytokines induce the downregulation of ephrin-B1 in adipose cells, suggesting that obesity not only promotes the secretion of cytokines but also influences the structure of the gastrointestinal mucosa through cytokine secretion." (PMID 35949596, 2022). "In obesity, reduction of adipose EFNB1 may accelerate the vicious cycle involved in adipose tissue inflammation." (PMID 24098442, 2013). "In obesity, under-expression of EFNB1 in adipose tissue may accelerate the vicious cycle of adipose tissue inflammation." (PMID 24098442, 2013). "Ephrin-B1 (EfnB1) was selected among genes of unknown function in adipocytes or adipose tissue and subjected to thorough analysis to understand its role in the development of obesity." (PMID 24098442, 2013). "The obesity-induced secretion of inflammatory cytokines, including MCP-1, drive carcinogenesis by downregulating ephrin-B1 expression." (PMID 35949596, 2022). "Obesity induces the secretion of inflammatory cytokines in adipose tissue, such as MCP-1 and tumour necrosis factor-α (TNF-α) via activation of the ERK, nuclear factor-κB (NFκB), and c-Jun N-terminal kinase (JNK) pathways, which contribute to ephrin-B1 downregulation." (PMID 35949596, 2022).